RB1 (RB transcriptional corepressor 1)
Diseases named in the same sentence as RB1 in open-access papers (continued):
Sharing a sentence is not in itself a finding about the gene and the disease.
osteosarcoma (continued). "Also, mutations at the RB1 locus are present in 60%-70% of both familial and sporadic osteosarcomas." (PMID 26555075, 2015). "RB1 loss or mutation has been reported in a variety of solid tumors, including osteosarcoma." (PMID 25126591, 2014). "This suggests that both primary genetic and gene/environment interactions contribute to osteosarcoma development in the setting of a germline RB1 mutation, and this may also be the case in apparently sporadic osteosarcoma." (PMID 21437228, 2011). "Another tumor suppressor gene whose loss of expression is linked to osteosarcoma is RB1." (PMID 20465837, 2010). "Similarly, RB1 mutations may enhance the metastatic potential of osteosarcoma cells, making it imperative to integrate therapies that specifically address metastatic pathways alongside conventional treatments." (PMID 39896817, 2024). "Therefore, the HRD mutation signature observed in RB1-defective osteosarcoma tissues might suggest the potential sensitivity of PARPi in this patient." (PMID 38744935, 2024). "While previous studies, including our own, have implicated perturbation of RB1 signaling in Hh pathway activation in developmental and cancer models, we were unable to functionally show this by genetic inactivation experiments in the Rb1 WT 45Ca osteosarcoma cell lines." (PMID 37845394, 2023). "These patients often go on to develop secondary tumors in their bones (osteosarcomas), highlighting the importance of Rb1 dosage and function in bone growth and differentiation." (PMID 38248470, 2024).
osteosarcoma (continued). "The authors concluded that the data provide evidence that RB1 status is a predictor of single-agent PARPi sensitivity in osteosarcoma-derived cells, with sensitivity levels comparable to that of BRCA2-mutated cancer cells." (PMID 37373240, 2023). "Somatic RB1 alterations are present in about half of the sporadic cases of osteosarcoma, most often as deletions." (PMID 37894411, 2023). "Both RB1-null and RB1-wild-type osteosarcoma cell lines appeared to equally benefit from targeting UHRF1." (PMID 36068209, 2022). "Recurrent copy number changes were identified in regions containing canonical osteosarcoma-associated genes, such as MYC and RB1, as well as in more novel regions such as 13q34." (PMID 35887382, 2022). "Moreover, the degree to which UHRF1 loss reverted the increased malignancy upon Rb1 loss suggests that the benefit of UHRF1 targeting could go beyond the scope of osteosarcoma by improving current treatment paradigms of other cancers harboring RB/E2F pathway inactivation." (PMID 36068209, 2022).
osteosarcoma (continued). "Haploinsufficiency of RB1 leads to reduced TERRA levels, telomere shortening, and increased genomic instability, a common phenotypic feature of Rb1 deficient cells (i.e., osteosarcoma)." (PMID 35982970, 2022). "This presents a new mechanistic insight into RB1 loss-associated poor prognosis and novel oncogenic roles of UHRF1 in the regulation of angiogenesis and exosome secretion, both critical for osteosarcoma metastasis." (PMID 36068209, 2022). "Our group is the first to model the critical role of UHRF1 in osteosarcomagenesis, with Uhrf1 KO resulting in a dramatic increase in overall survival and a decrease in metastases, particularly in Rb1-null osteosarcoma." (PMID 36068209, 2022). "We therefore quantified RAD51 recruitment in RB1-defective osteosarcoma lines using ionising radiation (IR) to induce DDSBs." (PMID 34862364, 2021). "We validate the involvement of RB1 defects in this response and document single-agent PARPi efficacy in a preclinical model of RB1-mutant osteosarcoma." (PMID 34862364, 2021). "Collectively the data provide evidence that RB1 status is a predictor of single-agent PARPi sensitivity in osteosarcoma, with sensitivity levels comparable to that of BRCA2-mutant cells." (PMID 34862364, 2021). "We observed a significant DNA damage-dependent RAD51 recruitment, evidenced by increased numbers of cells with >15 RAD51 foci, and a significant increase in foci numbers per cell in all RB1-defective osteosarcoma lines except one, LM7." (PMID 34862364, 2021). "Both yielded significantly increased median sensitivity for the RB1-defective compared to the RB1-normal osteosarcoma group, with sensitivities across the RB1-defective group greater than, or closely matching that of BRCA2-mutated CAPAN1." (PMID 34862364, 2021). "RB1 was cotransfected in combination with increasing amounts of MmuPV1 E7 into SAOS-2 human osteosarcoma cells, which express an inactive, C-terminally truncated, barely detectable RB1 mutant." (PMID 34465025, 2021). "Similar to osteosarcoma, RB1 is suggested to be inactivated during their progression in a majority of cancer types." (PMID 34359636, 2021). "We observed a robust and significant rise in γH2AX-positive cells following treatment with PARPi olaparib in two different RB1-defective osteosarcoma lines, seen within 2 h but increasing with time of treatment." (PMID 34862364, 2021). "To begin to understand what causes the PARPi hypersensitivity in RB1-mutant cancer cells we assessed DDSB-damage response activation in RB1-defective and RB1-normal osteosarcoma cell lines." (PMID 34862364, 2021). "PARPi treatment results in extensive cell death in RB1-defective backgrounds and prolongs survival of mice carrying human RB1-defective osteosarcoma grafts." (PMID 34862364, 2021).
osteosarcoma (continued). "The highly penetrant hypersensitivity in RB1-defective osteosarcoma cells shown here combined with the currently limited options in patient with such cancers, advocates expansion of assessment to include RB1-mutated disease." (PMID 34862364, 2021). "Together these results are consistent with an enhanced sensitivity to PARPi in RB1-mutant osteosarcomas and identify rapid cell death as a key consequence of PARPi exposure in osteosarcoma cells with this genetic defect." (PMID 34862364, 2021). "Reportedly, RB1 inactivation occurs in 20~40% of osteosarcoma cases, yet it is thought to contribute to tumor progression based on pathological examination and linkage with unfavorable outcome." (PMID 34359636, 2021). "RB1 alterations also serve as unfavorable prognostic markers for the clinical classification and management of osteosarcoma patients." (PMID 33375764, 2020). "RABL6 regulated retinoblastoma 1 (Rb1) activity in osteosarcoma cells, which was the major player in cell cycle control." (PMID 32600359, 2020). "The second most frequently altered gene in osteosarcoma is RB1 (retinoblastoma 1), involved in blocking cells from entering S phase of the cell cycle." (PMID 31741049, 2020). "Osteosarcoma Saos2 cells harbor a homozygous deletion in the RB1 gene and are therefore resistant to palbociclib in the sense that they do not undergo neither cell-cycle arrest nor senescence." (PMID 30692638, 2019).
osteosarcoma (continued). "We suggest that the role of Rb1 as a tumour suppressor in osteosarcoma will be exerted by both canonical Rb1 activity on cell cycle transit, and telomere homeostasis." (PMID 28169375, 2017). "Amplification of CDK4 and loss of RB1, or CDKN2A loss are considered nearly universal in osteosarcoma with 20% of cases having either amplification of CDK4 or deletion of CDKN2A." (PMID 27074562, 2016). "In people, almost 70% of osteosarcomas have at least one RB1 gene alteration and the percentage is similar in dog osteosarcomas." (PMID 29056713, 2016). "We tested if co-deleting Rb1 and Pten in mouse osteo-progenitors resulted in osteosarcoma development." (PMID 26317218, 2015). "Rb1 hetero- or homo-zygous co-deletion greatly increases the incidence and the rapidity of onset of adipogenic tumors, again, with only rare osteosarcoma tumors." (PMID 26317218, 2015). "We also aged Osx1-Cre; Rbfl/+; Ptenfl/fl mice to determine of retaining a single copy of Rb1 promoted osteosarcoma formation." (PMID 26317218, 2015). "To determine if Rb1 and Pten synergize as tumor suppressor genes for osteosarcoma, we co-deleted them in osteoprogenitor cells." (PMID 26317218, 2015). "The RB1 tumor suppressor gene plays a key role in osteoblast and bone formation, and deletion or inactivation of RB1 is a frequent occurrence in osteosarcoma." (PMID 25126591, 2014). "Nearly all osteosarcomas are felt to have the RB1 pathway disrupted, some tumors accomplishing this with p16/INK4A silencing or CDK4/Cyclin D1 overexpression." (PMID 22550413, 2012). "Eight of the 53 chimeric mice observed developed osteosarcomas, most of which had lost heterozygosity for Rb1 in the tumor cells." (PMID 21403899, 2011).